RRM2 (ribonucleotide reductase regulatory subunit M2)
Diseases named in the same sentence as RRM2 in open-access papers (continued):
Sharing a sentence is not in itself a finding about the gene and the disease.
lung cancer (continued). "RRM2 overexpression, for example, promoted the gastric cancer invasion capacity, while its silencing inhibited the proliferation, invasion, and migration of lung cancer cells and other malignant phenotypes." (PMID 34434213, 2021). "Moreover, the expression levels of RRM2 in lung cancer tissues is also closely related to the prognosis of patients and the level of tumor-infiltrating CD8 + T cells." (PMID 34434213, 2021). "It was revealed that RRM2 was an independent prognostic marker in lung cancer in GSE30219 dataset." (PMID 32638267, 2020). "Similarly, the Kaplan-Meier survival analysis showed that pyrimidine metabolic rate–limiting enzymes DTYMK, NT5C3, RRM1, RRM2, TK1, TYMS, and UCK2 were all associated with adverse prognosis in the lung cancer." (PMID 32638267, 2020). "Furthermore, we found that pyrimidine metabolic rate–limiting enzymes CAD, RRM2, DTYMK, TYMS, TK2, and NR5C2 were all associated with the clinical outcomes of lung cancer and liver cancer." (PMID 32638267, 2020). "RRM2 regulates antiapoptotic protein Bcl-2 in head and neck and lung cancers." (PMID 31886214, 2019). "Recently, Xia Xu found that overexpression of p53R2 and RRM2 could selectively induce the occurrence of lung cancer in transgenic mice." (PMID 29246119, 2017). "In non-small cell lung cancer (NSCLC), RRM2 expression was strongly predictive of disease-specific survival in women, non-smokers and former smokers who had quit at least 10 years prior to being diagnosed with lung cancer." (PMID 26001082, 2015). "MMP11+RRM2 are up-regulated in lung cancer, pancreatic cancer and stomach cancer tissues, and hence may also make a good marker for these three cancer types." (PMID 21060876, 2010). "Additionally, low expression levels of RRM2 may be used to assess the response of lung cancer to cisplatin-based chemotherapy." (PMID 40732324, 2025). "There is increasing evidence that RRM2 may be a promising target for lung cancer treatment." (PMID 40732324, 2025). "Collectively, we reveal for the first time that Cyclin Y promotes lung cancer radioresistance by binding to Chk1 to activate RRM2/STAT3 signaling, indicating that targeting Cyclin Y may be a promising strategy for enhancing the efficacy of radiotherapy in the treatment of non-small cell lung cancer." (PMID 40083692, 2025). "We also demonstrated the expression RRM2 is elevated in lung cancer tissues and knockdown of RRM2 induces ferroptosis in lung cancer cells H1975.We propose potential immune subtypes of LUAD based on the FRG cluster analysis that may lead to improved treatment for LUAD." (PMID 36153508, 2022). "Finally, our results suggest that RRM2 is an important biomarker affecting the long-term survival of patients with LUAD, and silencing RRM2 could promote the occurrence of ferroptosis in lung cancer cells." (PMID 36153508, 2022). "Based on the observations that RNR was one of the afatinib-targeted proteins, we then further examined whether there was a combination effect of afatinib with gemcitabine (a well-known inhibitor of RNR) on the viability, RRM1 and RRM2 protein levels of human lung cancer cells." (PMID 29765556, 2018). "Coincidently, RRM2 could also increase Bcl-2 protein stability in Head and Neck and Lung Cancers." (PMID 27801665, 2016). "We also utilized two normal lung epithelial cell lines and seven lung cancer cell lines, and found that in lung cancer cell lines, the expression of MYBL2 and RRM2 is higher, which is consistent with the results from clinical samples." (PMID 40885709, 2025). "To evaluate the clinical significance of MYBL2-RRM2 axis in lung cancer, we first observed that MYBL2 and RRM2 are highly expressed in cancer tissues compared to adjacent normal tissues across multiple cancer types in TCGA." (PMID 40885709, 2025). "Dual-luciferase reporter assays in lung cancer cell lines (H2122 and H23) demonstrated that MYBL2 overexpression significantly enhanced RRM2 promoter activity." (PMID 40885709, 2025).
lung cancer (continued). "Cyclin Y interacts with Chk1, thereby activating the RRM2/STAT3 signaling pathway and promoting radioresistance in lung cancer." (PMID 40083692, 2025). "To validate MYBL2-mediated transcriptional regulation of RRM2 in KRAS G12C mutant lung cancer, we identified two putative MYBL2-binding motifs within the predicted RRM2 promoter region (-2000 to +60)." (PMID 40885709, 2025). "Although PBK, RRM2, and DLGAP5 are also significant in cancer biology, EXO1’s potential impact on lung cancer mechanisms and treatment is particularly noteworthy." (PMID 39777332, 2024). "To determine the clinical relevance of RRM2 expression, we detected RRM2 expression in a normal lung cell line (BEAS-2B) and seven lung cancer cell lines (H1299, A549, H460, H23, H838, PC-9, and H1975)." (PMID 36153508, 2022). "The protein expression levels of Cyclin E, cdc25A, ATM, p21, RRM2, γH2AX, and ATR/pATR were assessed via immunoblotting on samples from exponentially growing, untreated U2OS and lung cancer cells." (PMID 34359691, 2021). "And the pyrimidine metabolic rate–limiting enzymes DTYMK, NT5C3, RRM1, RRM2, TK1, TYMS, and UCK2 had particular values in lung cancer prognosis." (PMID 32638267, 2020). "Compared with the lung normal tissues, the pyrimidine metabolic rate–limiting enzymes CAD, RRM2, and TK1 were hypo-methylated in lung cancer tissues derived from GSE32867 dataset." (PMID 32638267, 2020). "We also examined the expression of RRM2 in five lung cancer cell lines (A549, SPCA-1, 95-D, PG-49, and NCI-H292), and the results showed that the expression level of RRM2 was significantly higher than that in the normal cell lines (BEAS-2B and HaCaT)." (PMID 33411689, 2020). "Silencing of Rrm1 and Rrm2 markedly enhanced the cytotoxicity of the topoisomerase I inhibitor camptothecin that might be exploited in chemotherapeutic strategies and RRM2 was shown to regulate Bcl-2 in lung cancers and considered to be a worthy target in cancer therapy." (PMID 27602772, 2016). "Furthermore, mRNA expression of RRM2 and GAPDH was assessed in three lung cancer cell lines (A549, NCI-H1395, and NCI-H1975) and normal lung epithelial cells (BEAS-2B) via RT-PCR, reinforcing the role of these prognostic genes in LUAD." (PMID 40341308, 2025). "Importantly, we demonstrate that Cyclin Y interacts with Chk1 to positively modulate the expression of RRM2 and activate STAT3 signaling, ultimately promoting radioresistance in lung cancer." (PMID 40083692, 2025). "The results together indicate that there is no combination effect of afatinib and gemcitabine on RRM2 in human lung cancer cells." (PMID 29765556, 2018). "Moreover, protein levels of RRM2 were slightly reduced in either MTHFD2 or SLC2A1 knockdown lung cancer cells, but no alteration of MTHFD1 and SLC2A1 in RRM2 knockdown cells." (PMID 33664854, 2021). "However, no studies have investigated the impact of RRM2 on EMT in lung cancer." (PMID 40732324, 2025). "Similar results were obtained in GSE62948 dataset that the DNA methylation intensity of CAD, RRM2, and TK1 was lower in lung cancer tissues, compared with normal lung tissues." (PMID 32638267, 2020).
pancreatic cancer (48 papers, 2007 to 2025). "RRM2 upregulates the apoptosis-associated factor Bcl-2 and reduces Cleaved Caspase-3 in pancreatic cancer." (PMID 35248107, 2022). "The overexpression of RRM2 has been associated with gemcitabine resistance and increased cellular invasiveness in vitro and high expression of RRM2 in pancreatic tumors is associated with reduced overall survival after resection." (PMID 29100320, 2017). "As regulators of the cell cycle, RRM1 and RRM2 are associated with gemcitabine resistance in pancreatic cancer." (PMID 28797284, 2017). "It was discovered that expression of ribonucleotide reductase regulatory subunit M2 (RRM2) is regulated by VASH2; immunohistochemical analysis demonstrated a positive association of VASH2 expression and RRM2 expression in human pancreatic cancer tissues." (PMID 28327155, 2017). "Furthermore, only scarce data have been reported on the association of RRM2 protein expression with clinical outcome of pancreatic cancer patients." (PMID 33670609, 2021). "In addition, clinical data demonstrated that patients who have elevated RRM2 expression had less response to gemcitabine-based chemotherapy, and high expression of RRM2 in pancreatic cancer is associated with a poor prognosis." (PMID 34575569, 2021). "As RRM2 expression was inhibited by GA, and RRM2 was associated with gemcitabine resistance, we investigated whether GA combined with gemcitabine had a synergistic effect against pancreatic cancer cells." (PMID 28797284, 2017). "In pancreatic cancer, silencing RRM2 inactivates the PI3K/AKT/mTOR pathway, and reciprocal regulation of RRM2 and mTOR occurs in mammalian cells." (PMID 41341853, 2025). "This ENO1-mediated aggregation of RRM2 protein increases the synthesis of dNTPs in pancreatic cancer cells, enhancing the resistance of pancreatic cancer to gemcitabine." (PMID 41455715, 2025). "For instance, E2F transcription factors have been observed to upregulate RRM2 in pancreatic cancer, while BRCA1 has been demonstrated to transcriptionally activate RRM2 in glioblastoma." (PMID 40083692, 2025). "Recent research shows that RRM2 promotes liver metastasis in pancreatic cancer by stabilizing YBX1 and activating the TGF-β pathway." (PMID 39766842, 2024). "Migration and invasion of gastric, and pancreas cancers were enhanced through the overexpression of RRM2 accompanied by raised MMP2 and MMP-9 levels, and activation of NF-KB and AKT signaling." (PMID 37529110, 2023). "As far as we know, apart from the current report, only several other studies to date have assessed the clinical value of RRM2 protein or mRNA in pancreatic cancer cohorts, and these studies have varied with regard to the impact of RRM2 on patient survival." (PMID 33670609, 2021). "Ribonucleotide reductase subunit M2 (RRM2) acts as an important gemcitabine resistance-related gene in pancreatic cancer (PC)." (PMID 30777929, 2019). "Taken together, these findings suggests that miR-20a-5p dramatically decreases in GEM-resistant pancreatic cancer cells and binds directly to the predicted sequence of RRM2 3′-UTR." (PMID 30777929, 2019). "The expression of the main four factors (hENT1, dCK, RRM1 and RRM2) involved in gemcitabine transport and metabolism was also shown to correlate with acquired resistance to gemcitabine in pancreatic cancer cells." (PMID 31652737, 2019). "Although RRM2 has been studied in colorectal cancer, non-small cell lung cancer, pancreatic cancer, adrenocortical cancer, and cervical cancer." (PMID 30286759, 2018). "A similar case was observed in pancreatic tumors where ribonucleotide reductase regulatory subunit M2 (RRM2) the target of gemcitabine is under direct control of miR-211 and let-7a." (PMID 29967761, 2018). "Collectively, these results indicate that VASH2 induces gemcitabine resistance via upregulation of RRM2 in human pancreatic cancer." (PMID 28327155, 2017).
pancreatic cancer (continued). "The GA treatment was found to enhance the sensitivity of pancreatic cancer cells to gemcitabine by inhibiting the expression of RRM2." (PMID 28797284, 2017). "Immunohistochemical analysis demonstrated that the expression of VASH2 was positively related to the RRM2 in human pancreatic cancer tissues." (PMID 28327155, 2017). "The drug resistance genes, RRM1 and RRM2, reduce the pharmacological activity of gemcitabine by affecting its metabolism in pancreatic cancer cells." (PMID 28797284, 2017). "Here we report that the gemcitabine metabolism related gene, RRM2, is upregulated in pancreatic cancer models of VASH2 overexpression." (PMID 28327155, 2017). "It has been demonstrated that overexpression of RRM2 results in reduced gemcitabine sensitivity while RRM2 knockdown leads to enhanced gemcitabine sensitivity in pancreatic cancer cells and in human pancreatic cancer xenografts in mice models." (PMID 29144412, 2017). "In conclusion, PAUF was increased in pancreatic CSCs and the suppression of PAUF enhances chemotherapeutic response to gemcitabine and 5FU by decreasing MRP5 and RRM2 in pancreatic cancer cells." (PMID 29100320, 2017). "Previous studies have found that the expression of RRM1 and RRM2 in pancreatic cancer cells increases their sensitivity to gemcitabine." (PMID 28797284, 2017). "The synergistic killing of pancreatic tumor cells by combined treatment with ABC294640 plus gemcitabine is likely mediated by suppression of RRM2-mediated resistance in parallel with suppression of proliferation by the SphK2 inhibitor." (PMID 27517489, 2016). "Proof of this approach has been demonstrated by siRNA-mediated knockdown of RRM2 in colon and pancreatic cancer in vitro, which restored chemotherapeutic response to gemcitabine." (PMID 25499121, 2014). "The transcriptional upregulation of RRM1 and RRM2 has been consistently observed in pancreatic tumors resistant to gemcitabine and pancreatic cancer cell lines." (PMID 25402820, 2014). "Our study identified reduced let-7 expression to contribute to the RRM2-mediated inherent chemoresistance in poorly differentiated pancreatic cancer cells." (PMID 23335963, 2013). "Reduced expression of the majority of let-7 miRNAs with an inverse relationship to RRM2 expression was identified in innately gemcitabine-resistant pancreatic cancer cell lines." (PMID 23335963, 2013). "Intriguingly, overexpression of human precursor-let-7 miRNAs led to differential RRM2 expression and chemosensitivity responses in a poorly differentiated pancreatic cancer cell line, MIA PaCa-2." (PMID 23335963, 2013). "We first verified RRM2 expression in pancreatic cancer cell lines that were categorized earlier as inherently gemcitabine-sensitive or -resistant." (PMID 23335963, 2013). "Overexpression of ribonucleotide reductase subunit M2 (RRM2), involved in deoxyribonucleotide synthesis, drives the chemoresistance of pancreatic cancer to nucleoside analogs (e.g., gemcitabine)." (PMID 23335963, 2013). "Further, overexpression of let-7 was found to increase the radiosensitization of pancreatic tumor cells, while inhibition of RRM2 was identified to sensitize pancreatic tumors to ultraviolent radiation." (PMID 23335963, 2013). "Recent studies have shown that exogenous manipulations of RRM2 expression by siRNA or antisense oligonucleotides improve chemosensitivity in pancreatic cancer." (PMID 23335963, 2013). "The potential predictive role of RRM1 and RRM2 mRNA expression warrants examination in malignancies where gemcitabine-based therapy is standard, such as pancreatic cancer." (PMID 18414411, 2008). "The hENT1 × dCK/RRM1 × RRM2 ratio significantly correlated with the gemcitabine IC50 in eight pancreatic cancer cell lines (P=0.0029)." (PMID 17224927, 2007). "Notably, it has been demonstrated that upregulation of RRM2 leads to Gemcitabine chemo-resistance in pancreatic cancer (PC) cells and human PC xenografts in mice." (PMID 38619751, 2024).
pancreatic cancer (continued). "Interestingly, both RRM2 and DCK are reported to be associated with the drug sensitivity of gemcitabine (a common chemotherapeutic drug for pancreatic cancer and many other types of cancer)." (PMID 33520699, 2020). "Whereas low RRM2 expression in pancreatic cancers is predictive of greater response to gemcitabine." (PMID 30777929, 2019). "To investigate whether RRM2 affects GA-induced apoptosis of pancreatic cancer cells, we transfected PANC-1 and BxPC-3 cells with the RRM2 overexpression plasmid, following which they were subjected to treatment with GA for another 24 h." (PMID 28797284, 2017). "Furthermore, in clinical studies, mRNA levels of RRM2 inversely correlate with OS in gemcitabine-treated pancreatic cancer patients." (PMID 29144412, 2017). "Here, we found that VASH2 is expressed at high levels in human pancreatic cancer cells and acts as a gemcitabine-resistance factor, and the expression of RRM2 could be upregulated by VASH2 in a JUN-dependent manner." (PMID 28327155, 2017). "Consistently, earlier studies have implicated a causal relationship between let-7 and RRM2, identifying downregulation of many let-7 family members in RRM2-overexpressing, gemcitabine-resistant pancreatic cancer cells or a reduction in RRM2 expression after let-7 overexpression." (PMID 23335963, 2013). "In addition, distinct let-7 precursors were identified to improve chemosensitization in gemcitabine-resistant pancreatic cancer cells partially via post-transcriptional repression of RRM2." (PMID 23335963, 2013). "Hence, RRM2-independent drug-resistance mechanisms cannot be negated while considering nucleoside analog chemosensitization in pancreatic cancer cells." (PMID 23335963, 2013). "Based on computational predictions, we hypothesized that the let-7 tumor suppressor miRNAs will inhibit RRM2-mediated gemcitabine chemoresistance in pancreatic cancer." (PMID 23335963, 2013). "In summary, RRM2 was found to be a key determinant of both inherent and acquired gemcitabine with reduced let-7 expression likely to contribute to RRM2-mediated inherent chemoresistance in poorly differentiated pancreatic cancer cells." (PMID 23335963, 2013). "In this study, we established various gemcitabine-resistant subclones of human pancreatic cancer cell lines, and investigated changes in gene expression associated with gemcitabine transport and metabolism, that is, hENT1, dCK, RRM1, and RRM2 mRNA, in the development of gemcitabine resistance." (PMID 17224927, 2007). "Indeed, as one of the possible explanations for the apparent disagreements, it has recently been proposed that the prognostic implications of the expression profile of RRM2 could depend on the stage of pancreatic cancer." (PMID 33670609, 2021). "Additionally, miR-20-5p could target ribonucleotide reductase subunit M2 (RRM2) to regulate the gemcitabine chemosensitivity in pancreatic cancer cells and enhance the growth of triple-negative breast cancer (TNBC) cells by targeting Runx3, Bim, and p21." (PMID 34294156, 2021). "Ribonucleotide reductase M2 (RRM2) is the regulatory subunit of ribonucleotide reductase and is not only involved in the tumorigenesis and progression of a variety of carcinomas (such as colon, breast, and pancreatic cancer) but also leads to resistance to cancer chemotherapy." (PMID 31987036, 2020). "We explored whether GA affects the expression of RRM1 and RRM2 in pancreatic cancer cells." (PMID 28797284, 2017). "In addition, downregulation of RRM1 or RRM2 in pancreatic cancer cells could increase their chemosensitivity to gemcitabine." (PMID 28797284, 2017). "Suppression of RRM2 could sensitize colon and pancreatic cancer cells to chemotherapeutic agents." (PMID 26658059, 2015). "Therefore, part of the ability of PEG-ADI to increase the response of human pancreatic cancer cells to gemcitabine may be through abrogation of the compensatory cellular response of RRM2 induction." (PMID 25499121, 2014).